APOE (apolipoprotein E)
Diseases named in the same sentence as APOE in open-access papers (continued):
Sharing a sentence is not in itself a finding about the gene and the disease.
COVID-19 (continued). "With more COVID-19 test results (March 16 to May 31, 2020) and mortality data (to March 31, 2020, with incomplete data for April 2020) linked to UKB, we reevaluated the ApoE e4 allele association with COVID-19 test positivity, and with all-cause mortality following test-confirmed COVID-19." (PMID 32623451, 2020). "The presence of the ApoE ε4 genotype, albeit associated with a higher risk of SARS-CoV-2 infection and COVID-19 severity, did not appear to predispose for the presence of long COVID in our cohort of previously hospitalized COVID-19 survivors." (PMID 37510324, 2023). "ApoE4 reduces ACE2 expression and then imbalances the RAS system to more Ang II and less Ang 1–7 to increase inflammation, which has been reported to be a proposed mechanism for the ApoE genotype impacts COVID-19 outcomes." (PMID 36759834, 2023). "Additionally, the interactions between apoE and the ACE2 receptor should be investigated to determine the direct relationship between APOE and COVID-19." (PMID 36089575, 2022). "Furthermore, APOE ε4 carriers clinically correlate with increased SARS-CoV-2 infection and elevated serum inflammatory factors in 142 COVID-19 patients assessed." (PMID 35915083, 2022). "More research is needed to access genetic changes that may play a deleterious role in the clinical course of COVID-19 patients, including analysis of the ACE2 and APOE genes, major histocompatibility complex class I genes, Toll-like receptors, and others." (PMID 36412593, 2022). "However, the correlation between apoE and ACE2 levels should be examined in the context of COVID-19." (PMID 36089575, 2022). "In COVID-19 patients, we estimated a proper excess of 0.12 ± 0.06 mg/dl for NEFAs (p = 0.04), and reductions of 0.36 ± 0.10 mmol/L in HDL cholesterol (p < 0.01) and 116.05 ± 45.49 ug/ml in Apolipoprotein E (ApoE) concentrations (p = 0.01)." (PMID 34031519, 2021). "The underlying mechanisms of the pathogenesis and infection of S-COVID-19 could be better described by suggesting APP, EGF, C3, APOE, and APOA1 as the novel chief organizers of the network foundation." (PMID 33244380, 2020). "Interestingly, although macrophages were also present in healthy subjects and patients with mild COVID-19, they had different gene signatures, indicative of interstitial and cluster-0 macrophage (i.e., FABP4, APOC1, APOE, C1QB, and NURP1)." (PMID 33138195, 2020). "Third, due to a lack of clinical information, the APOE genotypes of patients in the AD group were ε3/ε3, while those in the COVID-19 group remain unclear." (PMID 36211330, 2022).
Brain atrophy (121 papers, 2006 to 2026). Partial or complete wasting (loss) of brain tissue that was once present. "In contrast, galantamine did not significantly reduce hippocampal atrophy in the overall analysis, but it was associated with reduced whole brain atrophy in APOE ε4 carriers." (PMID 39939901, 2025). "Conversely, galantamine was associated with a reduced rate of whole brain atrophy, presenting an adjusted mean difference of 0.17 (0.51), but this effect was only observed in APOE ε4 carriers." (PMID 39939901, 2025). "Multinomial regression revealed that higher education, larger hippocampal volume, and lower daily functional impairment were associated with reversion, whereas APOE ε4, poorer memory, and greater brain atrophy predicted progression (model accuracy: 78%)." (PMID 41301354, 2025). "Galantamine was associated with a reduced rate of whole brain atrophy, with an adjusted mean difference of 0.17 (0.51), but this effect was observed only in APOE ε4 carriers." (PMID 39939901, 2025). "Many studies report the impact of APOE polymorphisms on brain atrophy in AD progression and link ε4 with faster cortical thinning and hippocampal atrophy, with increasing effects as patients get older." (PMID 37333001, 2023). "GWAS also highlight APOE as the genetic variant mostly associated with brain atrophy and cortical thinning across lifespan, with a stronger effect for subjects with brain disorders." (PMID 37333001, 2023). "Sex is as important a risk factor as APOE-ε4 genotype for cortical thinning and brain atrophy for AD patients, as both stratification yield effect sizes that are not significantly different." (PMID 37333001, 2023). "We have also highlighted how whole-brain atrophy acceleration is associated with AD-PRS outside the APOE locus in healthy individuals." (PMID 36523268, 2022). "Female APOE-e4 carriers develop AD more frequently than age-matched males and have more brain atrophy and memory loss." (PMID 35573689, 2022). "We found that the effect of the APOE-ε4 allele on brain atrophy in the disease groups differs from that in the control group." (PMID 34721251, 2021). "As it has been suggested that APOE is associated to Aβ deposition, with APOE ε2 carriers displaying less pathology, we also investigated a possible influence of APOE on the degree of brain atrophy." (PMID 28886705, 2017). "This stratified analysis showed that the association between galantamine treatment and lower whole brain atrophy rate was confined to carriers of an APOE ε4 allele." (PMID 25478019, 2014). "MCI patients who carried an APOE ε4 allele and were treated with galantamine showed 36% less whole brain atrophy compared with those who were treated with placebo." (PMID 25478019, 2014). "As reported in many studies, age; ApoE-ε4 alleles; being widowed, divorced, or living alone; brain atrophy; and depressive symptoms are positively associated with conversion to MCI in our cohort." (PMID 39081990, 2023). "We evaluated the cerebral morphological changes of various groups and the effect of APOE-ε4 on brain atrophy, structural association between the NBM and amygdala, and the association between volumetric changes and neurocognitive performance, focusing on the cholinergic brain regions." (PMID 34721251, 2021). "Indeed, the effect of the APOE ε4 genotype has been reported to be more deleterious in younger subjects, with accelerated rates of brain atrophy in regions particularly susceptible to deposition of neurofibrillary tangles and neuronal loss." (PMID 31920926, 2019). "It is still not fully known through which mechanisms APOE and other genes with smaller effect impact AD risk, but brain atrophy level and cognitive function are considered intermediate phenotypes that may mediate genetic effects on AD risk." (PMID 29760643, 2018).
Brain atrophy (continued). "Lower levels of vascular endothelial growth factor (VEGF) were positively associated with all three atrophy measures after adjusting for baseline brain volumes and t-tau and remained associated with higher whole brain atrophy (P=0.023) after adjusting for p-tau, age, APOE status and sex." (PMID 25072324, 2014). "It is plausible that a higher proportion of APOE ε4 carriers are on a path to clinical disease manifestation of AD, putatively driven by the spreading of Tau deposition, which is strongly linked to steeper brain atrophy, memory decline, and short-term clinical diagnosis." (PMID 41271752, 2025). "For example, null associations are reported for APOE genotype and cross-sectional hippocampal volume, brain atrophy, GM volume and some WM measures, though APOE e4 carriers exhibited greater WM hyperintensity growth over a 3-year period in older age when compared to non-e4 carriers." (PMID 30903549, 2020). "The reduction in ApoE may not only worsen the cholesterol metabolism but also exacerbate amyloid plaque formation, which will trigger microglial activation and inflammation, leading to neuronal loss and brain atrophy." (PMID 32751716, 2020). "APOE ε4 is associated with hippocampal, amygdala, and entorhinal cortex atrophy, increased brain atrophy, increased white matter hyperintensity volumes and altered cerebral blood flow and glucose metabolism, however the mechanisms for these changes remain unclear." (PMID 20576093, 2010). "The APOE genotype has previously been shown to influence the rate of brain atrophy over time and regional changes in brain function during cognitive tasks." (PMID 40456910, 2025). "Numerous studies have demonstrated that the administration of IGF-1 lessened brain atrophy, brain insulin resistance, apolipoprotein E-related neuropathology, and neurotransmitter secretion." (PMID 38473814, 2024). "This includes factors such as Aβ deposition, APOE ε4 carrier status, brain atrophy severity, and inflammatory markers." (PMID 39286460, 2024). "In addition, we revealed the CHD- and APOE gene-varying associations between QT prolongation and brain atrophy, suggesting that CVD may be involved in the association of ECG markers with brain atrophic lesions, and that APOE ε4 allele may share a different pathophysiological process." (PMID 38956440, 2024). "APOE ε4 promotes increased tau deposition and brain atrophy in carriers compared to non‐carriers, which is proposed to be mediated by glia." (PMID 38477490, 2024). "More specifically, lower LDL-associated ApoJ and plasma and HDL-associated ApoE levels were significantly associated with CSO-EPVS, lower ApoJ content in HDL with brain atrophy and lower ApoE content in LDL with the extent of cSS." (PMID 37113571, 2023). "Last year, a clinical research team combined plasma p-Tau, ApoE genotype and MRI brain atrophy measurements to accurately predict Aβ PET deposition." (PMID 37333457, 2023). "The goal of this work was to study how brain atrophy is affected by factors such as age, the APOE gene, sex, and the level of education completed." (PMID 36295023, 2022). "With respect to APOE genotype effects on AD pathology, the most compelling results published to date describe the differing regional patterns of brain atrophy observed in APOE4+ vs. APOE4− AD patients." (PMID 33148345, 2020). "Interestingly, AD patients carrying the APOE ε4 allele show a more profound loss in cholinergic activity in the hippocampus and the cortex, and in neuroimaging studies the presence of the APOE ε4 allele was associated with a greater rate of hippocampal, cortical, and whole-brain atrophy." (PMID 32823921, 2020). "Our study demonstrates that there is a dose-dependent effect of the APOE genotype on the regional brain atrophy." (PMID 31920926, 2019). "In our sensitivity analysis, which additionally adjusted for APOE ε4 status, the effect of the MeDi on total brain atrophy became slightly larger." (PMID 28053008, 2017).
Brain atrophy (continued). "Predictive accuracy was further increased using APOE ε4 status and whole-brain atrophy (as indexed by brain parenchymal fraction)." (PMID 26537709, 2015). "Lower levels of TFF3 were consistently associated with greater ventricular expansion (P<0.001), hippocampal atrophy rate (P<0.001) and whole brain atrophy rate (P<0.001) even after adjusting for baseline brain volumes, t-tau, p-tau, age, APOE status and sex." (PMID 25072324, 2014). "In the APOE+ and amyloid+APOE+ groups hippocampal atrophy rate clearly occurred before brain atrophy rate." (PMID 25012224, 2014). "This protective effect of galantamine on whole brain atrophy rate in MCI was only present in APOE ε4 carriers." (PMID 25478019, 2014). "We found that galantamine only lowered the rate of brain atrophy in MCI patients who were APOE ε4 carriers." (PMID 25478019, 2014). "Lower levels of CgA were associated with higher whole brain atrophy and ventricular expansion when t-tau and baseline volume were included in the model; and with higher whole brain atrophy when p-tau, age, APOE status and sex were also included as covariates." (PMID 25072324, 2014). "This protective effect of galantamine on the whole brain atrophy rate in MCI was only present in APOE ε4 carriers." (PMID 25478019, 2014). "APOE ε4 carriers had higher whole brain atrophy rates (adjusted mean difference, 0.16% (95% CI, 0.02 to 0.30%)) and hippocampal atrophy rates (adjusted mean difference, 0.68% (95% CI, 0.28 to 1.07%)) compared with APOE ε4 noncarriers." (PMID 25478019, 2014). "As expected, subject groups also differed in terms of APOE ε4 dose, brain atrophy rate, WMH volume, and CSF tau levels, with these values increasing from controls to MCI to AD subjects." (PMID 23522844, 2013). "In this study, Vemuri and colleagues further demonstrated that changes in serial structural MRI differed by APOE ε4 status overall among aMCI, with higher brain atrophy rates in APOE ε4 carriers." (PMID 21949904, 2012). "In a recent work Zakrewska-Pniewska and co-workers analysed the relationship between APOE and MPO genes' polymorphisms and MS, and they found that the genotype GG of MPO was related to more pronounced brain atrophy." (PMID 16504169, 2006). "Our findings suggest that in older adults with mostly preserved cognition, baseline Aβ-PET predicts future brain atrophy, with fusiform atrophy showing independence from tau pathology and Aβ-dependent atrophy being exacerbated in region-dependent manners in females and APOE-ε4 carriers." (PMID 41270680, 2025). "Between-group differences in spatial navigation and associations with AD biomarkers and regional brain atrophy were not influenced by APOE genotype." (PMID 40456910, 2025). "APOE ε4 carriers, for example, appear particularly sensitive to air pollution–related brain atrophy: older women with APOE ε4 who lived near dense traffic exhibited significantly greater hippocampal volume loss than APOE ε4 non-carriers in the same environment." (PMID 41441202, 2025). "Moreover, Apoe deletion rescued brain atrophy and altered microglia and T cells, tying together the role of APOE and the innate and adaptive immune responses to tau vs. plaques via microglia." (PMID 39844286, 2025). "Our study extends this paradigm by incorporating accessible biomarkers of CVD into a model that already includes baseline demographics (age, sex), cognitive screening (MoCA), genetic information (APOE genotyping), along with clinically accessible neuroimaging measures of brain atrophy (MTL volume)." (PMID 39219209, 2024). "The associations of ECG parameters with structural brain MRI markers varied by CHD and APOE gene, such that prolonged QT and JTs interval were associated with brain atrophy only among individuals who had CHD or did not carry the APOE ε4 allele." (PMID 38956440, 2024).
Brain atrophy (continued). "This might be explained by the low prevalence of the APOE‐ε4 genotype in our study population and the uncertain effect of the APOE‐ε4 genotype on brain atrophy in healthy participants." (PMID 35021194, 2022). "In contrast, risk factors (such as age, APOE, or health risks) and markers that quantify general brain atrophy and regional cortical brain structure did not add markedly to model performance." (PMID 35878565, 2022). "Considering that female APOE-e4 carriers are more likely to progress from MCI to AD, develop AD more frequently than age-matched males, and have more brain atrophy and memory loss, we next sought to determine if these biological factors impact CSF EV miRNA cargo." (PMID 35573689, 2022). "For LMCI and AD groups, APOE-ε4 allele carriers exhibited higher brain atrophy than non-carriers in the cholinergic pathway." (PMID 34721251, 2021). "Third, as with all observational studies, although we adjusted for multiple potential confounders, we cannot exclude the possibility of residual confounding, including, but not limited to, ApoE genotyping, social factors, brain atrophy, and cerebral small vessel disease." (PMID 35250530, 2021). "The stronger correlation between brain atrophy and cognitive performance for APOE-ε4 carriers may imply that APOE-ε4 carriers rely on the compensatory brain system to achieve memory performance equivalent to non-carriers." (PMID 34721251, 2021). "We confirmed the APOE-ε4 effect on the brain atrophy in the cholinergic projections." (PMID 34721251, 2021). "ApoE ɛ4 carriers have lower concentrations of Aβ1–42, higher total tau and phosphorylated-tau, and a higher degree of brain atrophy than individuals without ApoE ɛ4 allele." (PMID 32587611, 2020). "Taken together, frailty biomarkers, APOE, and age-related memory decline may share common pathophysiological mechanisms (i.e., brain atrophy, beta-amyloid burden, inflammatory markers)." (PMID 31221191, 2019). "Predictors of this conversion include whether the patients are carriers of ε4 alleles of the apolipoprotein E (APOE) gene, brain atrophy, clinical severity, patterns of cerebrospinal fluid (CSF) biomarkers, cerebral glucose metabolism, and A(β) deposition." (PMID 31584953, 2019). "Given the intimate link between tau pathology and neurodegeneration in neuroimaging, neuropathology, and cell and animal studies, it is possible that APOE ε4 status affects the spread of tau in AD and subsequent brain atrophy, but only few studies have explored this." (PMID 30086796, 2018). "The present study evaluated the integration and relative value of spatial patterns of brain atrophy (SPARE-AD index), CSF biomarkers, measures of cognitive performance (ADAS-Cog), along with APOE genotype, in predicting the individual risk of converting from MCI to AD." (PMID 24371799, 2014). "Lower levels of Chromogranin-A (CgA) were associated with higher whole brain atrophy (0.008) and ventricular expansion (0.009) after adjusting for baseline volumes and t-tau and predicts higher whole brain atrophy (P=0.009) after additionally adjusting for p-tau, age, ApoE status and sex." (PMID 25072324, 2014). "After additionally adjusting for p-tau, age, ApoE status and sex and with FDR correction to control for multiple comparisons, 4/83 analytes were associated with whole brain atrophy rate, 1/83 analyte with ventricular expansion rate, and 2/83 with hippocampal atrophy rate." (PMID 25072324, 2014). "Moreover, APOC1 polymorphism influences HV, which may have a significant effect on brain atrophy compared to that of APOE." (PMID 40369256, 2025). "While reporting that APOE ε2/ε4 may be involved in accelerating brain atrophy or reduction of dopaminergic neurons (as quantified by DAT striatal binding ratio (SBr)) in PD, we also report that subjects with PD exhibit intrinsic heterogeneity, which may stem from genetic factors." (PMID 40018689, 2025).